DGKD (diacylglycerol kinase delta)
Description:
Diacylglycerol kinase that converts diacylglycerol/DAG into phosphatidic acid/phosphatidate/PA and regulates the respective levels of these two bioactive lipids. Thereby, acts as a central switch between the signaling pathways activated by these second messengers with different cellular targets and opposite effects in numerous biological processes (Probable). By controlling the levels of diacylglycerol, regulates for instance the PKC and EGF receptor signaling pathways and plays a crucial role during development (By similarity). May also regulate clathrin-dependent endocytosis.
Synonyms: DGK-delta; KIAA0145; DGKdelta; dgkd-2
Tractability: Antibody: UniProt places it where antibodies can reach, with high confidence; its Gene Ontology location is reachable by antibodies, with high confidence. PROTAC: ubiquitination databases record sites on it; its protein half-life has been measured.
Target class: Enzyme; Transferase
Gene: Protein-coding gene on chromosome 2 (233,354,484 to 233,472,104, forward strand). Ensembl gene ENSG00000077044.
Subcellular location: Membrane, clathrin-coated pit; Cytoplasm; Cell membrane (Isoform 1)
Subcellular location (Human Protein Atlas): Cytosol
Pathways (Reactome):
Hemostasis: Effects of PIP2 hydrolysis
Gene Ontology:
Molecular function: ATP-dependent diacylglycerol kinase activity; identical protein binding; kinase binding; protein binding; protein heterodimerization activity; protein homodimerization activity; diacylglycerol binding; kinase activity
Biological process: diacylglycerol metabolic process; lipid phosphorylation; phosphatidic acid biosynthetic process; positive regulation of clathrin-dependent endocytosis; intracellular signal transduction; negative regulation of phospholipase C/protein kinase C signal transduction; platelet activation; positive regulation of epidermal growth factor receptor signaling pathway; signal transduction; diacylglycerol catabolic process; glycerolipid metabolic process; phosphatidic acid metabolic process; phospholipase C-activating G protein-coupled receptor signaling pathway
Cellular component: clathrin-coated pit; cytoplasm; cytosol; plasma membrane; nucleus
Genetic constraint (gnomAD): Loss-of-function variants: 65 observed, 145.98 expected, observed/expected ratio (o/e) 0.45, 90% interval 0.36 to 0.55. The upper end of that interval is the gene's LOEUF score, 0.55, which puts it in group 2 of 6, group 1 being the genes least tolerant of losing a copy. Missense variants: 1,309 observed, 1,561.4 expected, observed/expected ratio (o/e) 0.84, 90% interval 0.8 to 0.88. Synonymous variants: 671 observed, 633.67 expected, observed/expected ratio (o/e) 1.06, 90% interval 0.99 to 1.13.
Homologues: Orthologues: chimpanzee DGKD (97% identical), macaque DGKD (96% identical), mouse Dgkd (94% identical), rat Dgkd (94% identical), pig DGKD (94% identical), guinea pig DGKD (89% identical), dog DGKD (88% identical), rabbit DGKD (82% identical), tropical clawed frog dgkd (76% identical), Drosophila melanogaster CG34384 (50% identical), Caenorhabditis elegans dgk-4 (30% identical), zebrafish DGKD (26% identical), and 2 more. Paralogues in human: DGKH (65% identical), DGKK (38% identical), DGKG (20% identical), DGKB (19% identical), DGKZ (19% identical), DGKI (19% identical), DGKQ (19% identical), DGKA (19% identical), DGKE (17% identical).
Diseases named in the same sentence as DGKD in open-access papers:
DGKD is named in the same sentence as 34 diseases in open-access papers, as found by Europe PMC text mining. Sharing a sentence is not in itself a finding about the gene and the disease. The quoted sentences say what the papers report.
Insulin resistance (5 papers, 2020 to 2024). Increased resistance towards insulin, that is, diminished effectiveness of insulin in reducing blood glucose levels. "DGKδ is the primary isoform in skeletal muscle and adipose tissue, where reduced expression is associated with insulin resistance in diabetic individuals." (PMID 39684917, 2024). "Peripheral insulin resistance and moderate obesity are implicated in decreased DGKd protein expression." (PMID 38916734, 2024). "DGKδ deficiency exacerbates hyperglycemia-induced peripheral insulin resistance and plays a critical role in the progression of type 2 diabetes." (PMID 39684917, 2024). "All these findings suggest that a reduction in DGKδ can lead to obesity through increases in insulin resistance and metabolic inflexibility." (PMID 37107557, 2023). "This could provide pharmacological strategies that target DAG and PA metabolism through DGKd modulation, potentially preventing and controlling insulin resistance in metabolic disorders." (PMID 38916734, 2024).
type 2 diabetes (4 papers, 2021 to 2025). "DGKδ deficiency impairs energy metabolism while exacerbating type 2 diabetes." (PMID 41080753, 2025). "In skeletal muscle, DGKδ is a critical enzyme in the pathogenesis of type 2 diabetes mellitus, and in the brain, it regulates the serotonergic system." (PMID 41080753, 2025). "DGKδ is an essential enzyme in the suppression of the pathogenesis of type 2 diabetes and its upregulation is important for the prevention and treatment of the disease." (PMID 36685282, 2022). "Recently, we demonstrated that SMSr interacted with the δ isozyme of DG kinase (DGKδ), which is involved in the pathogenesis of type 2 diabetes, obsessive–compulsive disorder, and epidermal growth factor–dependent cell proliferation, via their sterile α motif domains (SAMDs)." (PMID 33621517, 2021).
coronary artery disease (2 papers, 2016 to 2024). "Polymorphisms in genes associated with the regulation of calcium levels (CASR, CYP24A1, CARS, DGKD, DGKH/KIAA0564 and GATA3) and metalloproteinases (MMP-3 and MMP-9) were also associated with an increased risk of coronary artery disease and AMI." (PMID 38478535, 2024).
diabetes (2 papers, 2021 to 2023). "It was discovered that DGKD overexpression could protect and improve glucose homeostasis in diabetes by AMPK-related signal transduction and lipid metabolism." (PMID 34322485, 2021).
Hyperglycemia (2 papers, 2015 to 2024). An increased concentration of glucose in the blood. "DGKδ deficiency leads to hyperglycemia, peripheral insulin resistance, and metabolic inflexibility." (PMID 25847921, 2015).
kidney stone (2 papers, 2022 to 2025). "Moreover, additional studies are required to define the cells and tissues via which impaired DGKδ-mediated CaSR signal transduction causes increased kidney stone risk." (PMID 40372791, 2025). "In conclusion, this study defines 3 common putative KSD-causing variants and demonstrates the central role of the DGKδ-mediated reduction of CaSR signal transduction, increased renal phosphate excretion, and perturbed 1,25 vitamin D inactivation in kidney stone pathogenesis." (PMID 40372791, 2025). "Furthermore, we demonstrate that cinacalcet, a positive CaSR allosteric modulator, ameliorated impaired CaSR-mediated signaling due to rare kidney stone–associated DGKδ missense mutations and normalized biased CaSR signal transduction in DGKδ-depleted cells." (PMID 40372791, 2025). "Moreover, our functional studies of rare coding, KSD-associated DGKD variants are consistent with DGKδ-mediated impaired CaSR signal transduction in the pathophysiology of nephrolithiasis." (PMID 40372791, 2025). "A recent meta-analysis identified 20 nephrolithiasis-associated loci, including CYP24A1, DGKD, DGKH, WDR72, GPIC1, and BCR locus which were predicted to affect vitamin D metabolism and calcium-sensing receptor signaling respectively." (PMID 35439979, 2022). "Our studies, which have not examined the physiological effects of DGKδ dysfunction, indicate that additional investigations are required to define the cells and tissues via which impaired DGKδ-mediated signal transduction via the CaSR and other GPCRs may cause increased kidney stone risk." (PMID 40372791, 2025).
obsessive-compulsive disorder (2 papers, 2021 to 2024). A disorder characterized by the presence of persistent and recurrent irrational thoughts (obsessions), resulting in marked anxiety and repetitive excessive behaviors (compulsions) as a way to try to decrease that anxiety. "Decrease in Myristic acid production results in the deficiency of DGKδ, and subsequently induces obsessive-compulsive disorder (OCD)-like behavior through enhancing axon/neurite outgrowth in DGKδ-KO mice." (PMID 34475403, 2021). "Brain-specific DGKδ knockout mice exhibited obsessive-compulsive disorder-like behaviors sensitive to SERT inhibitor, and SERT protein levels are markedly elevated in the DGKδ-deficient brain." (PMID 39684917, 2024).
acute monocytic leukemia (1 paper, 2023). Acute monoblastic leukemia (AML-M5), is one of the most common subtypes of acute myeloid leukemia (AML) that is either comprised of more than 80% of monoblasts (AML-M5a) or 30-80% monoblasts with (pro)monocytic differentiation (AML-M5b). "DGKH consistently showed the lowest expression except in acute monocytic leukemia (AMOL), while DGKZ, DGKD, DGKQ and DGKA exhibited the highest expression levels." (PMID 37509516, 2023).
acute myeloid leukemia (1 paper, 2023). Acute myeloid leukemia (AML) is a group of neoplasms arising from precursor cells committed to the myeloid cell-line differentiation. "According to cancer expression databases, acute myeloid leukemia (AML) exhibits significant overexpression of multiple DGK isoforms, including DGKA, DGKD and DGKG, without a precise correlation with specific AML subtypes." (PMID 37509516, 2023).
atopic dermatitis (1 paper, 2025). "Phenome-wide association study data suggested that modulating DGKD, CASR, CYP24A1, or SLC34A1 may result in target-mediated adverse effects including alterations in serum bilirubin, inflammatory bowel disease, migraine, atopic dermatitis, and eczematous phenotypes." (PMID 40372791, 2025).
diabetic retinopathy (1 paper, 2012). "Using Wiki-Pi, we infer that its association to diabetic retinopathy may be mediated through its interactions with the genes HSPB1, KRAS, TMSB4X and DGKD, and that it may be involved in cellular response to external stimuli, cytoskeletal organization and regulation of molecular activity." (PMID 23209562, 2012).
esophageal cancer (1 paper, 2024). A primary or metastatic malignant neoplasm involving the esophagus. "Among negatively correlated genes, a higher expression of CLDNI5 and IL2RG, and was seen in esophageal cancer than normal tissue (p < .05), but the converse was true for DGKD, CLDNI8, TMEM220-AS1, TMEM220, C3orf86, and SSR2 (p < .0.05)." (PMID 38241178, 2024).
hyperparathyroidism (1 paper, 2025). Hyperfunction of the parathyroid glands resulting in the overproduction of parathyroid hormone. "This is similar to our findings of hyperparathyroidism in individuals with KSD carrying the DGKδ Q190 and W1181 variants." (PMID 40372791, 2025). "Thus, DGKδ-associated perturbations of CaSR signal transduction may have intracellular and tissue-specific effects that mirror CaSR loss-of-function variants associated with hyperparathyroidism phenotypes." (PMID 40372791, 2025).
lung carcinoma (1 paper, 2023). "Additionally, over-expression of SLFN13 and DGKD confers poor prognosis to the lung cancer patients and the ovarian cancer." (PMID 37024523, 2023).
major depressive disorder (1 paper, 2020). An episode of depression lasting two or more weeks without an intervening episode of mania. "For example, 1-stearoyl-2-docosahexaenoyl-PA produced by DGKδ interacts with and activates Praja-1, the E3 ubiquitin ligase acting on the serotonin transporter, which is a target of drugs for obsessive-compulsive and major depressive disorders, in the brain." (PMID 32947951, 2020).
malignant pleural mesothelioma (1 paper, 2025). A malignant neoplasm that arises from mesothelial cells in the pleura and shows a diffuse growth pattern. "In a kinome, CRISPR‐Cas9 knockout screen in which kinases in malignant pleural mesothelioma (MPM) cancer cells were targeted WEE1, AURKA, MPP3, MAP3K12, DGKD and SPEG could be identified as candidate genes." (PMID 40242936, 2025).
meningioma (1 paper, 2023). A generally slow growing tumor attached to the dura mater. "In the study, miR-3605-5p, miR-664b-5p, PNRC2, BTBD8, SLFN13, DGKD, NSD2, EXTL2, and BVES were closely corrected with the malignant progression of meningioma." (PMID 37024523, 2023).
prostate carcinoma (1 paper, 2012). A carcinoma that arises from epithelial cells of the prostate gland. "This study demonstrates the applicability of lentiviral-based shRNA for conducting phenotypic screens and identifies MAP3K11, DGKD, ICK, CIT, GALK2, and PSKH1 as regulators of prostate cancer cell growth." (PMID 22761715, 2012). "This study further demonstrates the applicability of lentiviral based shRNA for conducting phenotypic screens to identify targets involved in a variety of biological processes, and establishes MAP3K11, DGKD, ICK, CIT, GALK2, and PSKH1 as regulators of prostate cancer cell growth." (PMID 22761715, 2012).
tumor (3 papers, 2013 to 2023). "A total of 120 (27.9%) tumor samples harbored mutations in glycerolipid metabolism-related genes, with two genes identified as high frequently mutated, including DGKB (15%) and DGKD (14%)." (PMID 35600382, 2022). "Using healthy donor CD34+ cells as a reference, we detected overexpression of DGKA, DGKG, DGKD and DGKQ in tumor samples, while DGKH and DGKZ were unchanged." (PMID 37509516, 2023).
DGKD also shares sentences with these, for which no sentence is quoted: cancer (4 papers); Obesity (3); autosomal dominant hypocalcemia (1); cervical cancer (1); familial hypocalciuric hypercalcemia (1); Hypercalciuria (1); hyperphosphatemia (1); hypophosphatemia (1); infection (1); inflammatory bowel disease (1); liposarcoma (1); migraine (1); neuroblastoma (1); pancreatic cancer (1); Wilms tumor (1).